OGT (O-linked N-acetylglucosamine (GlcNAc) transferase)
Diseases named in the same sentence as OGT in open-access papers (continued):
Sharing a sentence is not in itself a finding about the gene and the disease.
cancer (continued). "Furthermore, we will discuss the potential and challenges in targeting OGT and O-GlcNAc as an approach to combat cancer." (PMID 37838167, 2023). "In addition to directly regulating cancer stem-like cell properties, OGT and O-GlcNAc also modulate the expression and activity of other factors to induce stem-like cell traits in cancer." (PMID 37838167, 2023). "Investigational OGT inhibitor is an ideal potential therapeutic option for cancers." (PMID 36980207, 2023). "Together, these challenges have slowed the testing of OGT inhibitors in preclinical cancer models." (PMID 37838167, 2023). "Together, these studies suggest that a combination of TRAIL and OGT inhibition may induce synergistic effects and provide a promising therapeutic strategy for the treatment of various cancers." (PMID 36059648, 2022). "This is a prevailing mechanism of the abnormal OGT/OGA networks underlying cancer development, also in line with the fact that O-GlcNAcylation is essential for transcription and translation, which are often reprogramed in cancer." (PMID 36291918, 2022). "Clearly, OGT acts at multiple points to enable cancer cells’ adaptive response to CDK9 inhibition." (PMID 35708495, 2022). "Notably, dysregulation of OGT, OGA, and the associated cellular O-GlcNAc profile is commonly detected in all cancers." (PMID 36291918, 2022). "This knowledge will not only aid in defining the malfunctions of OGT/OGA in complex diseases such as cancer, but also facilitate the development of novel strategies to manipulate the interactions of these enzymes and a subset of proteins without global O-GlcNAc perturbation-induced side effects." (PMID 36291918, 2022). "Many cancer types display elevated O-GlcNAcylation and abnormal OGT and OGA expression." (PMID 36439421, 2022). "Cancer cells elevate total O-GlcNAcylation by increasing OGT and/or decreasing OGA levels." (PMID 36439421, 2022). "Second, systematic analyses of OGT/OGA PPIs in cancer models." (PMID 36291918, 2022). "These preclinical findings suggest that the development of a novel treatment option using either cancer gene therapy with anti-OGT siRNA alone or in combination with GEM or PTX for UCB patients may be efficacious." (PMID 35625898, 2022). "Distinct OGT expression was observed in 25 of the 32 cancers included in this study." (PMID 35356257, 2022). "Interestingly, UDP-GlcNAc, the substrate used by OGT to O-GlcNAcylate proteins, is produced in the hexosamine biosynthetic pathway from glucose and glutamine, two obligatory nutrients for cancer cells." (PMID 35296731, 2022). "Increased O-GlcNAc transferase (OGT) expression has been reported in many human cancers." (PMID 36544170, 2022). "Based on the ESTIMATE algorithm, negative associations of OGT expression with the stromal score, immune score, and/or estimated score were detected in most of the cancers." (PMID 35356257, 2022). "Third, representative examples of OGT/OGA rewired PPIs that drive cancer malfunctions." (PMID 36291918, 2022). "Recently, a few OGT adaptors have been identified in different types of cancer cells." (PMID 36291918, 2022). "Based on the findings of this study, OGT inhibitors might be an alternative or adjunctive treatment for cancers with CPS1 overexpression." (PMID 36064721, 2022). "This implicates potentially distinct roles of different OGT isoforms in cancer cells." (PMID 36291918, 2022). "Therefore, inhibition of OGT is a strategy that can provide a benefit to chemotherapy by sensitizing cancer cells to anticancer agents or overcoming drug resistance in cancer." (PMID 36439421, 2022). "Overall, these studies have begun to uncover the abnormal PPIs of OGT/OGA in cancer models." (PMID 36291918, 2022). "The upregulation of OGT expression was detected in four cancers—CHOL, HNSC, LAML, and READ." (PMID 35356257, 2022). "In clinical outcomes, OGT expression plays different roles in various cancers." (PMID 35356257, 2022).
cancer (continued). "Therefore, there is an urgent need for an OGT inhibitor with better specificity, potency, and cell permeability, both for laboratory studies and clinical cancer therapy." (PMID 36104770, 2022). "Blocking OGT would then be expected to protect cancer cells in these conditions." (PMID 34868034, 2021). "Thus, as a regulator of NRF1, OGT is a promising target for use in combination with proteasome inhibitors as an anti-cancer therapy." (PMID 33535386, 2021). "Homeostasis of O-GlcNAc through activities of OGT and OGA has been previously implicated in normal hematopoietic development 96, 97, in differentiation arrest of AML and Jurkat T‐cells 98 as well as in other cancers." (PMID 34646384, 2021). "Another option might be to try to identify cancer cell specific vulnerabilities that are lethal in the presence of a low dose of an OGT inhibitor." (PMID 34868034, 2021). "The deficiency of OGT reduces alpha-ketoglutarate levels, which is a metabolite essential for the degradation of HIF-1α via its hydroxylation by HIF-PHDs, indicating that upregulated O-GlcNAcylation enhances HIF-1α activity and cell survival in cancer cells." (PMID 33535386, 2021). "Taken together, these observations are consistent with a view that O-GlcNAcylation may sustain cancer cells and that blocking OGT and the hexosamine pathway offers a novel approach to treatment for many cancers including CLL." (PMID 34868034, 2021). "Indeed, several studies have shown that cancer-related glucose metabolism dysregulation correlates with a rise in OGT expression and global levels of OGlcNAcylation in malignant cells." (PMID 33828530, 2021). "O-GlcNAcylation may be reduced in cancer cells either through small molecule inhibitors of OGT or through inhibitors mimicking UDP-GlcNAc, the substrate of OGT25,26." (PMID 33941787, 2021). "Next, to evaluate whether OGT regulates the expression of EZH2 to influence live cancer progression, OGT was overexpressed or silenced EZH2 in HCC‐LM3 and Huh‐7 cells as follows, oe‐NC + si‐NC, oe‐OGT + si‐NC, and oe‐OGT + si‐EZH2." (PMID 34510715, 2021). "OGT mRNA is significantly increased in metastatic prostate cancers compared with primary cancers." (PMID 33535386, 2021). "Moreover, data of aberrant OGT level in various cancer tissues is also collected and analyzed by UALCAN based on TCGA datasets." (PMID 33194731, 2020). "Moreover, the enhancement of cellular O-GlcNAcylation by PUGNAc in cancer cells with OGT knockdown, will notably reduce PFKFB3-S172 phosphorylation, increase PFKFB3 nuclear localization and block hypoxia-induced p27 accumulation." (PMID 32060258, 2020). "Moreover, decreasing O-GlcNAcylation levels via OGT knockdown or microRNA (miRNA; e.g., miR-483 and miR-24-1)-mediated depletion suppresses the growth, migration, and invasive capability of cancer cells." (PMID 33194731, 2020). "In cells, OGA can interact with OGT to form an “O-GlcNAczyme” complex under high glucose conditions, however disrupting this balance will lead to abnormal cell function and possibly even cancer." (PMID 33194731, 2020). "Activation of NF-κB via O-GlcNAcylation, therefore, modulates the expression of a variety of downstream genes involved in both tumor suppression and progression, indicating a role of OGT in regulating cancer metastasis by changing the NF-κB activation through its O-GlcNAc modification." (PMID 33194731, 2020). "This promotes hyper O-GlcNAcylation, which explains the abundance of OGT in cancer cells." (PMID 33251387, 2020). "In view of the important roles of O-GlcNAcylation in multiple fundamental cellular processes, it is unsurprising that imbalanced profiles of OGT/O-GlcNAcylation frequently lead to the occurrence of many diseases such as diabetes, neurological disorders, cardiovascular disease, and even cancer." (PMID 33194731, 2020). "OGT is overexpressed in various cancer cells and plays an important role in their growth." (PMID 32994395, 2020).
cancer (continued). "This variation in the effectiveness of XIAP to OGT regulation may be a product of the differences in the pool of O-GlcNAc-modified proteins in specific cancer types." (PMID 32994395, 2020). "Therefore, our findings regarding the reciprocal regulation of OGT and XIAP provide a novel molecular mechanism for controlling cancer growth and invasion regulated by OGT and O-GlcNAc modification." (PMID 32994395, 2020). "Importantly, reversing metabolic stress by overexpression of glucose transporter 1 (GLUT1) or reversing ER stress by depleting CHOP reversed OGT-depleted cancer cell metabolic stress and apoptosis." (PMID 31272438, 2019). "Interestingly, upregulated OGT activity in cancer cells leads to O-GlcNAcylation on FH-Ser75, competes with AMPK-mediated phosphorylation, compromises FH–ATF2 signaling, and prevents tumor growth arrest." (PMID 31272438, 2019). "In this review, we summarized evidences that OGT and O-GlcNAcylation intimately regulate the functions of the Polycomb group proteins at different levels especially during Drosophila melanogaster embryonic development and in human cancer cell lines." (PMID 30873122, 2019). "Importantly, overexpression of OGT and hyper O-GlcNAcylation of proteins have been emerging for the last decade as a landmark of cancer cells." (PMID 30853938, 2019). "Finally, biochemical and cell imaging experiments in human cancer cells reveal that the O-GlcNAc transferase (OGT) binds to and glycosylates cyclin D1." (PMID 30853938, 2019). "To prove this hypothesis, we knocked down OGT in two different cancer cell lines, MDA-MB-231 and NCI-H460, and examined the amount of bortezomib-induced cell death." (PMID 29941490, 2018). "Hence in cancer cells, where OGT activity is particularly high, pS75 levels are relatively low, conferring growth advantage to cancer cells." (PMID 30105004, 2018). "In addition, wide-ranging roles of OGT in cancer development and progression have been described, providing a rationale for targeting OGT in anticancer therapies." (PMID 29941490, 2018). "In this sense, targeting OGT in cancer cells and/or adapting patients to low caloric diet could increase the efficiency of anti-PI3K/AKT/mTOR therapeutic strategies and foil drug resistance." (PMID 30356686, 2018). "Specifically, the increase of the OGT has been observed in different types of tumor, such as breast, colon, liver, endometrial, cervical, lung, prostate and pancreatic cancer, and it has often been associated with a parallel decrease of either the OGA levels or the OGA/OGT ratio." (PMID 29865240, 2018). "Equally important, OGT also regulates lipid metabolism in cancer." (PMID 30105004, 2018). "We propose that metabolic reprogramming of cancers allows highly expressed OGT to maximally contribute to O-GlcNAcylation and to eventually develop dependence on the UPS and resistance to proteasome inhibitors by enhancing NRF1-mediated transcriptional activation of proteasome subunit genes." (PMID 29941490, 2018). "OGT and O-GlcNAcylation levels are elevated in several cancer types." (PMID 29435130, 2018). "More precisely, inactivation of AMPK by OGT was shown to regulate sterol regulatory element-binding protein-1 phosphorylation and stability, resulting in higher lipid synthesis and, subsequently, in elevated cancer cell growth and survival." (PMID 30271380, 2018). "OGT appears to be a clear regulator of AMPK activity in cancer development." (PMID 30237786, 2018).
cancer (continued). "Furthermore, complex interaction of OGT and Hif‐1 was reported in research of cancer, which indicates that OGT regulates Hif‐1 signaling to catalyze O‐GlcNAcylation reprogramming cancer cell metabolic and survival response." (PMID 29511617, 2018). "Intriguingly, OGT stability is regulated by the E3 ubiquitin ligase LSD2 in cancer cells." (PMID 30400201, 2018). "According to OGT is an important and indispensable enzyme in cell metabolic pathway, unbalanced O-GlcNAc modification on substrate proteins leads to various kinds of diseases, such as diabetes, neurologic disorders, cardiovascular disease, and cancer." (PMID 28488246, 2017). "TETs-OGT/O-GlcNAcylation is involved in some cancer development." (PMID 28488246, 2017). "Therefore, figuring out the mechanism of the network between OGT and epigenetic changes in tumorigenesis will provide a novel theoretical basis for cancer research." (PMID 28488246, 2017). "Importantly, our present quantitative model validates the critical role of OGT in regulating cancer development and recovery in multiple tumor types." (PMID 27703839, 2016). "Moreover, when comparing the OGT gene expression profile of DLBCL with that of other types of cancers, we consistently noted that DLBCL is one of the few malignancies that exhibit high OGT mRNA expression levels." (PMID 27716624, 2016). "OGT inhibition might sensitize cancer cells to DNA damage inducing agents, and this approach clearly demands further research." (PMID 26824323, 2016). "In addition, through the increased flux of HBP, cancer cells display higher levels of OGT and, therefore, of O-GlcNAcylation." (PMID 26835421, 2016). "OGT is also of high importance in normal cells, and combinatorial targeting of OGT and cancer-cell specific metabolic abnormalities may allow significant dose reduction." (PMID 26824323, 2016). "Taken together, mechanism-based therapies that are designed to target hyper O-GlcNAcylation and OGT may hold clinical benefits in the treatment of cancer." (PMID 27703839, 2016). "This study and others show that OGT and O-GlcNAcylation levels are increased in cancer cell lines." (PMID 27252680, 2016). "In sum, elevated protein O-GlcNAcylation and OGT expression have been reported in numerous malignancies including breast, prostate, lung, pancreas, liver, and colon cancers." (PMID 27148477, 2016). "However, we suggest that cancer cell lines are highly sensitive to metabolic deprivation and OGT knockdown, accordingly to their high-demand in nutrients, in particular glucose and glutamine." (PMID 27252680, 2016). "Further studies might include measuring relative levels of OGT and O-GlcNAc between PBMCs and cancer cell lines we used, based on information from previous work, along with testing of other sensitizers that we have not used." (PMID 26670328, 2015). "Thus, manipulation of O-GlcNAc levels using chemical or shRNA-mediated inhibition of OGA or OGT affects in vitro and in vivo migration/invasion of breast, lung, liver, prostate, and colon cancer cells." (PMID 23964270, 2013). "Interestingly, recent work also suggested alink between PI-3 kinase activity and OGT expression level in cancer cells." (PMID 23935944, 2013). "By contrast, tumor cell lines that mimic metastatic tumors showed an increase in OGT expression and O-GlcNAcation, suggesting that an increase in O-GlcNAcylation may be beneficial to cancer cells." (PMID 23554759, 2012). "Therefore, modulating O‐GlcNAcylation by inhibiting OGT activity may be a promising target for cancer treatment." (PMID 40237201, 2025). "Therefore, targeting OGT is a promising strategy for cancer treatment." (PMID 39285476, 2024). "Therefore, it is necessary to determine whether OGT and O-GlcNAcylation regulate cancer immunosuppression, immunotherapy, chemotherapy, and radiotherapy in HCC." (PMID 39199296, 2024). "However, the upstream role of OGT in cancer biology is poorly characterized." (PMID 38973004, 2024).
cancer (continued). "In the M2-macrophage-like TAMs, OGT directly modifies protease Cathepsin-B at Serine residue 210, which promotes maturation and secretion of Cathepsin-B to the tumor microenvironment to degrade the extracellular matrix supporting metastasis activities of cancer cells." (PMID 37838167, 2023). "In addition, many stem cell factors are directly O-GlcNAcylated, which could potentially contribute to cancer stem-like cell regulation by OGT/O-GlcNAc." (PMID 37838167, 2023). "In addition to glutamine, other amino acids in cancer cells are also regulated by OGT and O-GlcNAc." (PMID 37838167, 2023). "Therefore, targeting OGT and O-GlcNAc in combination with current treatments may have potential in improving anti-cancer therapy." (PMID 37838167, 2023). "Together, these recent findings show an emerging role of OGT and O-GlcNAc in regulating ferroptosis and survival, and targeting the O-GlcNAc cycle in combination with ferroptosis-inducing drugs could be a potential approach to targeting cancer." (PMID 37838167, 2023). "Thus, OGT-meditated O-GlcNAcylation may provide cancer cells with an advantage for sustained growth, immune evasion, and other hallmarks in the tumor microenvironment." (PMID 35356257, 2022). "Notably, aberrantly activated RAS/MAPK and PI3K/AKT pathways reportedly promote chemoresistance and metastatic progression in advanced UCB, and this oncogenic pathway activation also mediates an increase in OGT and overall O-GlcNAcylation in several cancers through increased glycolysis." (PMID 35625898, 2022). "Therefore, the expression of OGT often changes in diseases states, especially in various cancers." (PMID 36104770, 2022). "The elevated metabolic flux through the hexosamine biosynthetic pathway in cancer cells contributes to the increased production of uridine diphosphate N-acetylglucosamine (UDP-GlcNAc), which is the substrate of O-linked β-N-acetylglucosamine (O-GlcNAc) transferase (OGT)." (PMID 35625898, 2022). "Thus, distinct OGT expression may serve as an essential marker in the clinical management (e.g., targeted therapy) of some cancers." (PMID 35356257, 2022). "In addition to improve therapeutic efficacy and alleviate DOX resistance in different cancer types, therapy combination with OGT inhibition could allow the use of smaller doses of DOX, hence reducing the associated side effects." (PMID 36059648, 2022). "In summary, aberrant OGT–protein interactions and O-GlcNAcylation deregulate the assembly of the protein with other biomolecules, leading to diminished proteolysis and upregulated functions that may promote cancer cell growth." (PMID 36291918, 2022). "Thus, O-GlcNAcylated XIAP suppresses cancer cell growth and invasion by degrading OGT." (PMID 36291918, 2022). "The mechanisms of OGT in various cancers may be varied and complex." (PMID 35356257, 2022). "Whether OGT inhibition has cancer relevance in physiological settings is still somewhat unclear." (PMID 35868563, 2022). "However, it is not well known how OGT and O-GlcNAcylation levels are regulated in various cancers." (PMID 32994395, 2020). "Considering the critical function of aberrant O-GlcNAcylation in cancer progression and metastasis which has been summarized previously herein, it is likely that downregulation of hyper O-GlcNAcylation via OGT inhibition might not only slow cancer proliferation, but also cancer metastasis." (PMID 33194731, 2020). "Therefore, YAP1 may participate in cancer glycosylation metabolism through O-GlcNAcylation and OGT expression in order to maintain the abnormal proliferation and survival of cancer cells." (PMID 32390875, 2020). "Thus, the combination of chemotherapy and OGT inhibition may serve as a potential strategy to improve therapeutic efficacy in various cancers." (PMID 33121131, 2020).